ACOD1 (aconitate decarboxylase 1)
Diseases named in the same sentence as ACOD1 in open-access papers (continued):
Sharing a sentence is not in itself a finding about the gene and the disease.
colitis (continued). "Therefore, the role of Acod1-itaconate in colitis-related IBD and colorectal cancer is largely unknown." (PMID 35457208, 2022). "In the mice with DSS-induced colitis in vivo, CEP represses macrophage infiltration and ACOD1 expression in the colon tissues." (PMID 36770726, 2023). "We first confirmed the upregulation of Acod1 RNA and protein expression levels in DSS-induced colitis." (PMID 35457208, 2022). "In addition, it cannot be ruled out that a significant increase in DSS-induced colitis in the absence of ACOD1 deficiency is not just due to the absence of itaconate but that another mechanism may also exist." (PMID 35457208, 2022). "In model mice of colitis, Family XIII AD3011 group was positively correlated with the expression level of Aconitate decarboxylase 1 (ACOD1), which is highly expressed in colonic tissues in inflammatory diseases, whose expression is positively correlated with the severity of intestinal inflammation." (PMID 39315097, 2024). "Additionally, in the mouse model of DSS-induced colitis, CEP decreased macrophage infiltration and ACOD1 expression in colon tissue." (PMID 36770726, 2023). "Studies have indicated that Acod1 protein and mRNA levels are upregulated in DSS-induced colitis." (PMID 35457208, 2022). "PCR and WB showed that ACOD1 mRNA and protein levels were decreased in the CEP group, suggesting that CEP may regulate the expression of ACOD1 in activated macrophages under the condition of colitis." (PMID 36770726, 2023).
Obesity (8 papers, 2022 to 2025). Accumulation of substantial excess body fat. "To investigate the mechanism underlying the downregulation of ACOD1 in obesity, we focused on transcription factors that regulate ACOD1 expression." (PMID 39921443, 2025). "It is thus clear that Nrf2 activation is required during treatment of Acod1 and itaconate for pulmonary microvascular endotheliopathy caused by obesity." (PMID 38730297, 2024). "Querying for translational extension of data generated in mice, we retrieved ACOD1 expression in publicly available transcriptomic datasets of human subjects with obesity and the associated NAFLD." (PMID 38302438, 2024). "Consistent with obesity resistance, Acod1 loss lowered FITC-dextran levels increasing in serum of wild-type mice following oral dye administration, in response to HFD consumption, indicating preserved gut barrier function." (PMID 38302438, 2024). "By using whole-body indirect calorimetry, we demonstrated that Acod1 deficiency offers resistance to diet-induced obesity by stimulating energy expenditure." (PMID 38302438, 2024). "The observed reduction in ACOD1 expression in the context of obesity may be linked to suppressed transcription in macrophages." (PMID 39921443, 2025). "Both in vivo and in vitro experiments further suggested that this downregulation of ACOD1 in obesity may be linked to the upregulation of the transcriptional repressor GFI1 in alveolar macrophages." (PMID 39921443, 2025). "Prompted by such observations, we envisioned that resistance of Acod1-/- mice to diet-induced obesity might be functionally linked to changes in gut microbiota." (PMID 38302438, 2024). "Unveiling an unrecognized role of itaconate, either endogenously produced or exogenously administered, in supporting microbiota alterations underlying diet-induced obesity in mice, our study points ACOD1 as a target against inflammatory consequences of overnutrition." (PMID 38302438, 2024). "Therefore, to elaborate on the mechanisms responsible for resistance to diet-induced obesity and the associated metabolic dysfunctions promoted by Acod1 deficiency, we performed whole-body metabolic analyses of HFD-fed mice by indirect calorimetry." (PMID 38302438, 2024). "Consistent with resistance to diet-induced obesity, Acod1 deficiency decreases liver steatosis, dampening the hepatic accumulation of free fatty acids and associated diacylglycerol species, known to have causal roles in lipid-induced hepatic insulin resistance." (PMID 38302438, 2024). "Consistent with a less pronounced obesity-associated microbial signature, wild-type mice receiving fecal microbiota of Acod1-/- littermates gained less weight, showed lower fat depots and liver weights as well as increased insulin sensitivity, compared with wild type donors." (PMID 38302438, 2024). "Importantly, members of such taxa have already been extensively associated with protection from obesity and type 2 diabetes, in line with the amelioration of metabolic disease offered by Acod1 loss in mice." (PMID 38302438, 2024). "Such a conclusion derives from the evidence of dominant protective effects against adipose tissue accumulation, meta-inflammation, and obesity-associated metabolic dysfunctions offered by the transfer of fecal microbiota from HFD-fed Acod1-/- mice into wild-type counterparts." (PMID 38302438, 2024). "Importantly, members of such taxa have already been extensively associated with protection against obesity and type 2 diabetes in both mice and humans, in line with the leaner and metabolically healthier phenotype shown by Acod1-/- mice fed with HFD, compared with wild type controls." (PMID 38302438, 2024). "Western blot and immunofluorescence analyses further confirmed that ACOD1 protein levels were markedly lower in the lung tissue of patients with obesity." (PMID 39921443, 2025).
Obesity (continued). "In this study, we knocked down ACOD1 expression in the lungs of NCD mice to simulate the reduced levels seen in obesity, while overexpressing ACOD1 in HFD mice to reverse this downregulation." (PMID 39921443, 2025). "ACOD1 mRNA levels were significantly reduced in the lung tissue of patients with obesity compared to normal‐weight patients." (PMID 39921443, 2025). "Subsequent examination of lung tissue and primary alveolar macrophages from both human beings and mice confirmed that ACOD1 expression is reduced in alveolar macrophages in the context of obesity." (PMID 39921443, 2025). "Our findings highlight the critical protective role of ACOD1 in mitigating lung injury exacerbated by obesity and provide valuable insights for future research." (PMID 39921443, 2025). "In this study, we identified the downregulation of ACOD1 in alveolar macrophages in the context of obesity, confirmed its protective role in LPS‐induced ALI in HFD mice, and preliminarily elucidated its potential mechanisms of action and regulation." (PMID 39921443, 2025). "Further animal experiments revealed that GFI1 knockdown increased ACOD1 expression and alleviated LPS‐induced inflammation in obesity, indicating the critical role of GFI1 in exacerbating lung injury." (PMID 39921443, 2025). "Clinical samples are collected, an ALI model is established in HFD mice, and both human and mouse samples are analyzed, revealing a significant decrease in ACOD1 expression in lung tissue and alveolar macrophages in obesity." (PMID 39921443, 2025). "To further confirm the effects of obesity on ACOD1 expression, we established a mouse model of obesity by feeding mice an HFD for 16 weeks." (PMID 39921443, 2025). "Subsequent in vivo experiments targeting the regulation of ACOD1 specifically in pulmonary macrophages further confirmed that ACOD1's protective effects against obesity‐aggravated lung injury are macrophage‐mediated." (PMID 39921443, 2025). "In obesity, reduced ACOD1 expression in AMs worsens LPS-induced lung injury, possibly due to increased GFI1, a transcriptional repressor." (PMID 41039310, 2025). "In summary, these findings indicate that GFI1 suppresses ACOD1 transcription in the lungs in the context of obesity, exacerbating LPS‐induced lung injury, inflammation, and oxidative stress." (PMID 39921443, 2025). "Airway‐targeted knockdown of GFI1 restores ACOD1 expression in the lungs and partially alleviates the worsening of LPS‐induced lung injury in obesity." (PMID 39921443, 2025). "We further conducted targeted regulation of alveolar macrophages in vivo, strongly indicating that the protective effect of ACOD1 overexpression in obesity‐exacerbated acute lung injury is macrophage‐dependent." (PMID 39921443, 2025). "In our study, we found that, in the context of obesity, changes in ACOD1 protein and mRNA expression in alveolar macrophages were the primary factors contributing to the increased severity of lung injury." (PMID 39921443, 2025). "In conclusion, by specifically regulating ACOD1 expression in lung macrophages in vivo, we demonstrated that ACOD1 in macrophages plays a critical protective role in obesity‐aggravated lung injury." (PMID 39921443, 2025). "In line with this, analyses of a publically available transcriptomic dataset of human subjects with obesity retrieved colonic ACOD1 gene expression tied to obesity, altered glycemic control, and reduced expression of genes preserving gut barrier function." (PMID 38302438, 2024). "Here, we demonstrate that inhibition of itaconate biosynthesis, achieved by genetic disruption of Acod1 gene protects mice against diet-induced obesity by preserving a healthy gut microbiota opposing meta-inflammation and associated outcomes." (PMID 38302438, 2024). "Overall, these data indicate a dominant protective effect of fecal microbiota from Acod1-/- mice against diet-induced obesity." (PMID 38302438, 2024).
Obesity (continued). "Here, we demonstrate that ACOD1 responds to dietary lipid overload by promoting gut microbiota alterations supporting obesity and its major inflammatory outcomes." (PMID 38302438, 2024). "Moreover, nuclear factor erythroid 2‐related factor 2 (Nrf2) inhibition diminishes the protective effects of ACOD1 overexpression in ALI exacerbated by obesity." (PMID 39921443, 2025). "Similarly, the ACOD1 metabolite, itaconate, was also significantly reduced in the lung tissue of patients with obesity." (PMID 39921443, 2025). "Therefore, this study suggests that ACOD1 downregulation in alveolar macrophages is a key factor in worsening ALI in obesity, likely driven by GFI1 upregulation." (PMID 39921443, 2025). "To further investigate whether Nrf2 is a key downstream mediator of ACOD1's protective effects in exacerbated ALI in the context of obesity, we utilized the Nrf2 inhibitor ML385 in both in vivo and in vitro experiments." (PMID 39921443, 2025). "To further elucidate the role of GFI1 in regulating pulmonary ACOD1 expression in the context of obesity, we specifically knocked down GFI1 expression in the lungs of HFD mice via airway administration of adeno‐associated virus (shGFI1, 5 × 1012 vg ml−1; 100 μl mouse−1, 5 × 1011 vg mouse−1)." (PMID 39921443, 2025). "This aligns with previous findings in hepatic macrophages and pulmonary microvascular endothelial cells, indicating that ACOD1 expression may be altered in various tissues in the context of obesity." (PMID 39921443, 2025). "Collectively, these results demonstrate that deficiency of ACOD1 activity in mice offers an obvious amelioration - although not a complete abrogation - of diet-induced obesity and the associated alterations of glucose homeostasis." (PMID 38302438, 2024). "However, the effects of Acod1 and itaconate and the potential molecular mechanisms are still unclear in obesity-induced pulmonary microvascular endotheliopathy." (PMID 38730297, 2024). "It was preliminary demonstrated that Acod1 might play a critical role in obesity-induced pulmonary microvascular endotheliopathy by regulating immune, inflammation responses and the TCA cycle." (PMID 38730297, 2024). "Also, during the preparation of this manuscript, a report investigating the role of Acod1 in obesity has been released." (PMID 38302438, 2024). "Our findings suggested that Acod1/Itaconate axis might be an effective therapeutic treatment for mice with obesity-induced pulmonary microvascular endotheliopathy by activating Nrf2." (PMID 38730297, 2024). "Importantly, the amelioration of the mouse intestinal ecosystem, altered by HFD consumption, is not just the result of the protection from diet-induced obesity achieved by Acod1 deficiency, but contributes instrumentally to generate it." (PMID 38302438, 2024). "Therefore, we envisioned that the effects of Acod1 ablation in counteracting meta-inflammation and obesity sequelae might be secondary to changes in gut microbiota, contributing to regulate inflammatory responses and metabolic health in the host." (PMID 38302438, 2024). "Consistent with fecal microbiota alterations, HFD consumption resulted in decreased SCFA levels in stools of wild-type mice, with Acod1 loss counteracting such decline, pointing toward an amelioration of an obesity-associated intestinal ecosystem in the absence of itaconate." (PMID 38302438, 2024). "In conclusion, this study demonstrated that in the context of obesity, GFI1 protein levels are significantly elevated in alveolar macrophages, leading to the suppression of ACOD1 expression." (PMID 39921443, 2025). "In our previous study, we demonstrated that ACOD1 overexpression in the lungs of HFD mice, achieved via AAV‐ACOD1, mitigated obesity‐exacerbated lung injury." (PMID 39921443, 2025). "Additionally, in the context of obesity, growth factor independent 1 (GFI1) protein levels are elevated in alveolar macrophages, and its knockdown leads to upregulated ACOD1 expression." (PMID 39921443, 2025).
Obesity (continued). "However, consistent with obesity amelioration, such ratio in HFD-fed Acod1-/- mice was ~2.5-fold higher than in wild-type counterparts." (PMID 38302438, 2024). "While these results suggest obesity‐related reductions in ACOD1 expression across multiple organs, this study specifically focuses on the downregulation of ACOD1 in the lung and its contribution to the exacerbation of ALI following LPS exposure in the context of obesity." (PMID 39921443, 2025). "Further analysis revealed that the protective effects of macrophage‐targeted ACOD1 overexpression were not entirely eliminated by the Nrf2 inhibitor, suggesting the involvement of other downstream pathways in the exacerbation of lung injury in the context of obesity." (PMID 39921443, 2025).
pulmonary fibrosis (8 papers, 2022 to 2025). Chronic progressive interstitial lung disorder characterized by the replacement of the lung tissue by connective tissue, leading to progressive dyspnea, respiratory failure, or right heart failure. "Patients with idiopathic pulmonary fibrosis (IPF) showed decreased expression of ACOD1 in their airway macrophages and reduced levels of itaconate in their bronchoalveolar lavage." (PMID 38018224, 2024). "In a bleomycin-induced mouse model of pulmonary fibrosis, specific knockout of ACOD1 resulted in exacerbation of the disease." (PMID 39354366, 2024). "In contrast to our findings, others demonstrated that Acod1−/− animals had increased inflammatory/fibrotic consequences in a model of bleomycin-induced pulmonary fibrosis, suggesting that ACOD1 was important in limiting profibrotic and tissue remodeling processes." (PMID 39351225, 2024). "In the bleomycin mouse model of pulmonary fibrosis, Acod1 and itaconate were highly expressed." (PMID 38018224, 2024). "In addition, adoptive transfer of WT but not Acod1–/– monocyte–derived airway macrophages into the airway of Acod1–/– mice improved the outcome of bleomycin-induced pulmonary fibrosis, which further supports the importance of Acod1-expressing macrophages." (PMID 38085578, 2023). "Likewise, Acod1 and itaconate were also increased in ocular bacterial infection and idiopathic pulmonary fibrosis in mice." (PMID 38085578, 2023). "The expression of ACOD1 in alveolar macrophages (AMs) and itaconate levels in bronchoalveolar lavage fluid were both reduced in patients with idiopathic pulmonary fibrosis (IPF), indicating a significant alteration in the ACOD1/itaconate axis in fibrotic lung tissue." (PMID 39354366, 2024). "Studies of preclinical mouse models suggest that Acod1 and itaconate attenuate various noninfectious inflammatory conditions that involve macrophages, such as psoriasis, ischemia-reperfusion injury of both the brain and heart, lung fibrosis, and abdominal aortic aneurysms." (PMID 38085578, 2023).
ovarian carcinoma (7 papers, 2018 to 2025). A malignant neoplasm originating from the surface ovarian epithelium. "We have also shown that ACOD1-/- MSLN-CAR-iMACs combined with low dose ICIs could further elevated anti-ovarian cancer capacity." (PMID 37723178, 2023). "ACOD1-/- MSLN-CAR-iMACs expressed more pro-inflammatory marker proteins (CD80 and CD86) after being co-cultured with HO-8910 ovarian cancer cells for 24 h." (PMID 37723178, 2023).
breast cancer (6 papers, 2021 to 2025). A primary or metastatic malignant neoplasm involving the breast. "Furthermore, tumor-infiltrating neutrophils use aconitate decarboxylase 1 (Acod1) to make itaconate, which regulates Nrf2-dependent ferroptosis and leads to the metastasis of breast cancer to the lungs by up-regulating the GM-CSF-JAK/STAT5-C/EBPb pathway." (PMID 39925807, 2025). "However, on the base of the scRNA-Seq data of murine mammary tumor models, aconitate decarboxylase 1 (Acod1) emerges as the most upregulated metabolic enzyme in mouse tumor-associated neutrophils (TANs)." (PMID 39614322, 2024).
Arthritis (4 papers, 2023 to 2025). Inflammation of a joint. "Arthritis development in the K/BxN serum transfer model is accompanied by much osteoblast‐derived formation of new bone, and this new bone formation was found to be deficient in Irg1−/− mice compared with Irg1+/+ mice, indicating a role for Acod1 in the formation of this new bone." (PMID 40170391, 2025). "We also assessed the presentation of Lyme arthritis in both Acod1-/- and WT mice by collecting joints for histological analysis of arthritis at three weeks post infection and extracted DNA from the bladder for bacterial loads." (PMID 38157387, 2023). "It is note-worthy that the immune consequences of an Acod1 deficiency are tissue specific, primarily affecting carditis but not arthritis." (PMID 38157387, 2023). "Together, our data suggests that prolonged Bb infection results in induction of Acod1 which is necessary to suppress Lyme carditis, but not arthritis." (PMID 38157387, 2023).